AR (androgen receptor)
Diseases named in the same sentence as AR in open-access papers (continued):
Sharing a sentence is not in itself a finding about the gene and the disease.
prostate carcinoma (continued). "PIM1 is a kinase that is overexpressed in prostate cancer, while the two isoforms, PIM-1S and PIM-1L, are the major mediators of AR serine 213 (Ser-213) and threonine 850 (Thr-850) phosphorylation." (PMID 32397108, 2020). "In support of this, prostate cancer cell migration, which results from EMT, was severely compromised to the same extent when either Twist1 or AR expression was diminished by siRNA." (PMID 32296610, 2020). "Studies have been identified that JMJD5 acts in the cyclin A1 coding region to regulate breast cancer cell proliferation, and as a dual coactivator of AR and PKM2 integrates AR/EZH2 network and tumor metabolism in prostate cancer." (PMID 32678829, 2020). "In prostate cancer, SF3B2 directly binds to CE3 of AR and controls alternative splicing of AR to produce AR-V7." (PMID 32106418, 2020). "Data were also produced demonstrating that prostate cancer cells can use alternative nuclear receptors signaling pathway, such as ESR1 instead of AR signaling, to propagate." (PMID 32041153, 2020). "Nevertheless, the majority of advanced-stage prostate cancer patients, including those with SPINK1-positive subtype, are treated with AR-antagonists." (PMID 31959826, 2020). "In conclusion, current studies confirmed the critical roles of AR and TGF-β signaling in prostate cancer development." (PMID 32842649, 2020). "Since the androgen receptor (AR) signaling plays a critical role in the development and progression of prostate cancer (PCa), androgen deprivation therapy (ADT) or AR antagonists remain the standard treatment for PCa patients." (PMID 32904490, 2020). "According to the reported results, the expression of AR and IGF-1 in prostate cancer decreased as the expression of AMACR decreased." (PMID 32760737, 2020). "Encouraged by the positive clinical results of enzalutamide, two other second-generation AR antagonists, apalutamide, and darolutamide have recently been approved by the FDA for the treatment of prostate cancer." (PMID 32456317, 2020). "We observe that these six CREs can be bound by multiple TFs in prostate cancer cells, including FOXA1, AR, and HOXB13." (PMID 31974375, 2020). "The androgen receptor and myeloblastosis transcription factors have been reported to regulate expression of an overlapping set of DDR genes in prostate cancer cells." (PMID 32238799, 2020). "In prostate cancer, FOXA1 is known to pioneer and reprogram the binding of the androgen receptor (AR) alongside HOXB1318." (PMID 31974375, 2020). "In patients with prostate cancer, [18F]FDHT PET was used to determine the optimal dose of the AR blocker enzalutamide in a phase 1 trial." (PMID 32722205, 2020). "Univariate and multivariate regression analysis of genotypes and alleleof PTEN, AKT1, PI3K, AR, and AMACR genesin controls and patients with prostate cancer." (PMID 32484847, 2020). "In summary, we show that androgen receptor signaling stimulates DNA repair in part through increasing basal levels of PARG expression, suggesting a novel therapeutic target for prostate cancer patients with advanced disease." (PMID 32123273, 2020). "Blockade of AR signaling with ADT upregulates PARP activity and is necessary for prostate cancer cell survival." (PMID 32180937, 2020). "In prostate cancer, HOXB13 co-localizes with AR and acts as a repressor of AR target genes to modulate AR hormonal responses." (PMID 32546843, 2020). "Recent studies show that AR regulates some genes involved in DDR, and cooperates with Topo2a to contribute to prostate cancer progression." (PMID 32198885, 2020). "A study reported that ARs are the interacting partners of PARK7 in prostate cancer cells, and hormonal treatment enhances the formation of PARK7/AR complexes." (PMID 32357493, 2020). "Signal transduction crosstalk between AR and EGFR often leads to p38MAPK-dependent activation of mTOR and cyclinD1 expression in prostate cancer cells and in lung cancer cells." (PMID 32929340, 2020).
prostate carcinoma (continued). "In prostate cancer, FOXA1 also influences the ability of AR to bind DNA and control cell cycle progression." (PMID 33062889, 2020). "Nonetheless, three proteins, AR, FOXA1, and HOXB13, are also known to mediate prostate cancer progression, and their enrichment corresponded with u2j." (PMID 33322492, 2020). "As AR and HIF signaling pathways are major signaling hubs and oncogenic drivers of prostate cancer progression, this study aimed to investigate further the relationship between them." (PMID 32450824, 2020). "Ectopic PMEPA1 (isoform -b) degraded AR protein and decreased expression of AR responsive gene PSA in prostate cancer cells." (PMID 32842649, 2020). "Androgen receptor and OTR-colocalization was upregulated in androgen-independent human prostate cancer cells." (PMID 33193084, 2020). "Here, we included data on the TMPRSS2:ERG fusion (occurring in about 50% of prostate cancers), the most common recurrent chromosomal deletions (3p, 5q, 6q, 8p, 10q/PTEN, 12p, 12q, 13q, 16q, 17p, 18q), and the Ki67LI as well as AR protein expression levels." (PMID 32417965, 2020). "The specific biomarkers also include more cancer-specific markers, such as HER2neu and MUC1 in breast cancer, androgen receptor (AR), early growth response gene (EGR) and PSA in prostate cancer." (PMID 32823926, 2020). "Here, they show that whilst SPINK1 is transcriptionally repressed by androgen receptor and its co-repressor REST, it is upregulated after androgen-deprivation therapy, which leads to neuroendocrine differentiation of prostate cancer cells." (PMID 31959826, 2020). "With prostate cancer progression to CRPC, AR levels and transcriptional outputs are significantly increased with a corresponding elevation of PARG expression." (PMID 32123273, 2020). "We found that there is a striking correlation between the strength of the HOXC4 or HOXC6 binding sites and the strength of the binding sites for the key prostate cancer transcription factors HOXB13, FOXA1, and AR." (PMID 32012197, 2020). "To investigate whether treatment with AR targeting agents affected the association of PC1 with tumor fraction, we used PCA eigenvectors to project the progression samples, healthy volunteer controls (0 tumor fraction), and the LNCaP prostate cancer cell line (100% tumor, 3 replicates)." (PMID 32149736, 2020). "The blocking of AR signaling can drive increased inflammation in prostate cancer cells by the induced expression of CCL2, promoting prostate cancer progression via activation of the STAT3 signaling pathway and recruitment of TAMs." (PMID 33076397, 2020). "In an analysis of AR+, ER− MDA-MB-453 cells, the AR cistrome was found to be more similar to that of ER in MCF-7 (AR−/ER+) cells compared to the AR cistrome in LNCaP prostate cancer cells." (PMID 33062889, 2020). "This group demonstrated that in prostate cancer cells, CDK5 directly phosphorylates the AR at Ser81." (PMID 31910742, 2020). "Prostate cancer frequently has changed metabolism and in accordance with this CAMKK2 has been found to be a target of AR which affects PCa cell growth, migration and survival." (PMID 32413024, 2020). "ADT inhibits systemic androgen production and thereby slows prostate cancer cell proliferation and disease progression by limiting testosterone (T) and dihydrotestosterone (DHT)-mediated activation of the androgen receptor (AR)." (PMID 32796613, 2020). "A recurrent fusion gene in prostate cancers, ERG (erythroblast transformation-specific related gene), was shown to interact and collaborate with AR through chromatin looping." (PMID 32634370, 2020). "In prostate cancer cells, SCD1 proteolytic cleavage generates a small peptide that activates androgen receptor (AR) signaling to promote cell proliferation." (PMID 31936134, 2020). "In another study, androgen receptor signaling was found to upregulate NANOG mRNA and protein, directly contributing towards prostate cancer." (PMID 32765953, 2020).
prostate carcinoma (continued). "This lead molecule effectively inhibits receptor activity in the low to mid micro-molar concentrations, AR-dependent prostate-specific antigen (PSA) secretion from a variety of prostate cancer cells, and 22Rv1 prostate cancer cell proliferation." (PMID 33202977, 2020). "Low-dose celecoxib combined with exisulind can affect the tumorigenesis of prostate cancer by regulating pathways such as EGFR, Akt, androgen receptor, and cyclin D1." (PMID 32913451, 2020). "Given the vast interest in the roles of mitochondria in tumor initiation and progression, the effects of the AR on the TCA cycle and OXPHOS in androgen-dependent prostate cancer cell lines have also been explored." (PMID 32927797, 2020). "From the TCGA data of 333 primary prostate cancer, ALDH1A3 correlated with AR signaling pathway and corresponding luminal signature." (PMID 32375698, 2020). "Taken together, our study implicates Carbidopa for the first time in effective suppression of prostate cancer via a mechanism, involving AHR-mediated proteasomal degradation of AR." (PMID 32404918, 2020). "Many studies have demonstrated that the regulation of AR is downstream of activated AKT; thus, AKT upregulates AR levels in prostate cancer." (PMID 32972001, 2020). "β-Catenin is a coactivator of AR, and activation of Wnt/β-catenin signaling was thought to account for CRPC growth and progress of prostate cancer." (PMID 32904490, 2020). "In castrate-resistant prostate cancer cells, DIM induced the expression of miR-34a which was accompanied by decreased self-renewal of prostate cancer cells and suppression of Notch-1 and androgen receptor signaling." (PMID 35582221, 2020). "Among the epigenetic regulators of AR, lysine-specific histone demethylase 1 (LSD1, also known as KDM1A) was discovered first, and its mechanism has been well studied in prostate cancer." (PMID 32847068, 2020). "For example, NTN3 is regulated by AR and EZH2 in prostate cancer, and also acts in the activation of the hormone ER pathway." (PMID 32251318, 2020). "Seahorse lipid extract (SHL) decreased androgen receptor (AR) and prostate-specific antigen (PSA) expression in dihydrotestosterone (DHT)-induced LNCaP cells of prostate cancer." (PMID 32972001, 2020). "Univariate regression analysis between genotypes of PTEN, AKT,PI3K, AR, and AMACR genes withclinicopathological features in prostate cancer patients." (PMID 32484847, 2020). "Collectively, these data suggest that AR induces expression of Twist1 via ETV1, leading to enhanced EMT and migration of prostate cancer cells." (PMID 32296610, 2020). "We found that treatment of prostate cancer cell lines in vitro with IL10 or enzalutamide induced markers of neuroendocrine differentiation and inhibited androgen receptor reporter activity." (PMID 32802517, 2020). "It was found to bind to H3T11P (PKN1-mediated histone H3 threonine 11 phosphorylation) upon androgen stimulation in androgen-dependent prostate cancer cells to recruit KMT2A complexes and induce the expression of androgen receptor target genes." (PMID 33302406, 2020). "Sustained androgen receptor (AR) signaling is the major driver of castration-resistant prostate cancer (CRPC) and promotes prostate cancer development through the regulation of not only transcription networks but also genomic stability and DNA repair." (PMID 33117814, 2020). "Prostate cancer cells and CRPC xenografts under enzalutamide or abiraterone present a high expression of LBD-truncated AR-V7 and AR-V567es that produce an overexpression of UBE2C gene leading to treatment resistance." (PMID 30642011, 2019). "In a prostate cancer mouse model (TRAMP mouse), IL-23 secreted from MDSCs can activate the androgen receptor pathway and promote cell survival and proliferation under an androgen-deprived condition." (PMID 30736371, 2019).
prostate carcinoma (continued). "Aberrant activation of the AR directly promotes prostate cancer cell growth and survival, and androgen deprivation therapy (ADT) has been a standard treatment for prostate cancer for many decades." (PMID 30677079, 2019). "In primary tumors, ERG is frequently overexpressed in prostate cancer due to genomic fusions, placing ERG under the control of AR regulated promoters." (PMID 31798767, 2019). "Studies showed that JQ1 blocked binding of the androgen receptor (AR) to the target gene by disrupting BRD4 and AR interaction in castration-resistant prostate cancer." (PMID 31320814, 2019). "The CCL2-CCR2 axis is negatively regulated by androgen/AR signaling, with the CCL22-CCR4 axis acting as a further downstream mediator, both of which promote prostate cancer cell migration." (PMID 30871130, 2019). "Prostate cancer (PCa) growth is driven by testosterone and the more potent DHT activation of the AR." (PMID 31622417, 2019). "We first surveyed the expression of ERα, ERβ, AR, and ZFHX3 in several prostate cancer cell lines by Western blotting." (PMID 30979864, 2019). "When AR-positive human prostate carcinoma LNCaP cell line was compared to PC-3 and DU145 AR-negative prostate cancer cell lines, the inhibitory action of FK506 on cell growth was evidenced only in the AR-positive cells when they were treated with steroid." (PMID 30717249, 2019). "The expression of the MAGE-A11 coactivator, which is recruited through androgen receptor NH2-terminal FxxLF motif, is increased in castration-resistant prostate cancer." (PMID 31552182, 2019). "In prostate cancer cell line PCa cells, PLZF was identified as a repressor of AR as well as an activator of regulated in development and DNA damage responses 1 (REDD1), which suppressed mTORC1." (PMID 31142324, 2019). "Without castration treatment, N-Myc overexpressing LNCaP xenografts displayed more neuroendocrine prostate cancer phenotypes (indicated by CgA and NSE staining) than control LNCaP xenografts which showed more PCA phenotypes (indicated by AR and PSA staining)." (PMID 30657058, 2019). "We present an optimized protocol to enhance the transcription factor profiling in human tumor tissue and successfully performed ChIP-seq for ERα, AR, and FOXA1 in primary breast, endometrium, and prostate cancer specimens." (PMID 30620009, 2019). "Further functional analysis of the significantly expressed genes shows that some important pathways are enriched, including PI3K/AKT/AR pathway, Ras pathway, MAPK pathway, JAK/STAT pathway, prostate cancer pathway, and WNT pathway, etc." (PMID 31504033, 2019). "In the colon cfDNA pool, TFs EVX2, DLX2, HNF1A, HNF4A, and HNF4G and TFs AR and HOXB13 in the prostate cancer cfDNA pool had increased accessibilities, whereas FOXA1 exceeded the >5 z-score threshold in both the prostate and breast pool." (PMID 31604930, 2019). "In prostate cancer cells, KDM4B expression, which correlates with the severity of tumor types, can cooperate with AR to induce the AR response." (PMID 30759871, 2019). "AR controls EGFR and ErbB2 expression in prostate cancer cells and in turn EGFR and ErbB2 concur to PCa progression activating AR signaling in hormone-poor conditions." (PMID 31816863, 2019). "CCL4 is involved in prostate carcinogenesis through macrophage AR signaling, while the CCL21-CCR7 axis in prostate cancer cells is activated by tumor necrotic factor, which is secreted when androgen/AR signaling is inhibited." (PMID 30871130, 2019). "By luciferase reporter assays and ChIP analyses, the miR-1-2 promoter region was shown to be activated by the AR, and miR-1 targeting ‘tyrosine-protein kinase’ (SRC) in DU145 derived prostate cancer cell lines." (PMID 31744106, 2019). "In prostate cancer, BET protein inhibitors modulate AR signaling and enhance the anti-androgenic effect of AR-targeted therapies in AR positive prostate cancer cells such as VCaP and LNCaP cells, making them suitable drugs for treatment of mCRPCs." (PMID 31143708, 2019).
prostate carcinoma (continued). "Loss of PTEN is one of the most common genomic alterations in prostate cancer, and there is a reciprocal feedback between activation of AKT signaling and AR signaling." (PMID 30773595, 2019). "While validating the suppressive activity of ERβ in AR-positive prostate cancer cells, these findings also indicate that downregulation of MYC also mediates ERβ’s tumor suppressor activity in AR-positive prostate cancer cells." (PMID 30979864, 2019). "A subtype of castrate-resistant prostate cancer, called treatment-induced neuroendocrine prostate cancer (NEPC), has occurred owing to the widespread use of AR blockers." (PMID 30939845, 2019). "In prostate cancer, miR-205-5p was shown to arrest cell growth by repressing the mitogen-activated protein kinase (MAPK) and androgen receptor (AR) pathways." (PMID 31752366, 2019). "With the advent of next-generation AR-targeted therapies (abiraterone acetate and enzalutamide), there is an increased burden of lethal therapy-resistant, NEPC prostate cancer for which current treatments are ineffective." (PMID 31835563, 2019). "There are several therapeutic options available for prostate cancer, including radiotherapy, ADT, second generation AR-signaling inhibitors, chemotherapy, and bone-targeted agents." (PMID 31689899, 2019). "Similar results were reported in a xenograft mouse model for prostate cancer, where EGCG inhibited the nuclear translocation of AR and its downstream effects." (PMID 30823649, 2019). "These authors analyzed 200 prostate cancer tissues from CRPC patients and observed three different patterns of AR expression: nuclear (n-AR), mixed nuclear/cytoplasmic (n/c-AR) and low/no expression (AR-/low)." (PMID 31366128, 2019). "After our first demonstration of CDK5 in prostate cancer cells, we also showed that CDK5 phosphorylates AR at Ser-81 in prostate cancer cells and regulates the stabilization of AR proteins, therefore, the prostate tumor growth was promoted." (PMID 31395805, 2019). "In this model, the AR controls expression of the master splicing regulator protein ESRP2, which then regulates the splicing patterns of key genes important for prostate cancer biology." (PMID 31478829, 2019). "To further validate the relationship between LBCS and AR, we evaluated the expression of LBCS and AR in 18 cases of prostate cancer tissue by ISH and immunohistochemistry (IHC)." (PMID 31221168, 2019). "In prostate cancer, CDK5 increased cell growth ability in an androgen receptor (AR)-independent manner." (PMID 31496920, 2019). "Treatment of prostate cancer cells with enzalutamide enhances recruitment of pioneer factor GATA2, AR, Mediator subunits MED1 and MED14, and RNA Pol II to regulatory elements of enzalutamide-responsive genes." (PMID 31501863, 2019). "For instance, in prostate cancer the inhibition of either of the key oncogenic pathways PI3K and AR, results in a feedback upregulation of the other pathway through induction of EGFR family RTK signaling." (PMID 31685861, 2019). "As CCL5 was unable to promote migration of LNCaP siAR cells, it was concluded that elevated CCL5 secretion by bone stromal cells from metastatic lesions induced prostate cancer cell migration in a CCL5-dependent manner, upstream of AR signaling." (PMID 30871130, 2019). "For example, HOXC6 and DLX1 genes, which are biomarkers and key players of prostate cancer development as well as genes involved cell cycle (CDK4, CDC23, MYC) and androgen signaling (AR, GRHL2) are found." (PMID 31515496, 2019). "There are several mechanisms, which center on the regulation of androgen receptor (AR) signaling, of ADT resistance that can contribute to the prostate cancer progression." (PMID 31013891, 2019). "Both AR and GR have a role in resistance to androgen deprivation therapy (ADT), the mainstay of treatment for late stage prostate cancer." (PMID 31861264, 2019).